FOXP3 (forkhead box P3)
Diseases named in the same sentence as FOXP3 in open-access papers (continued):
Sharing a sentence is not in itself a finding about the gene and the disease.
atherosclerosis (continued). "Forkhead Box P3 (FOXP3), an immune-related gene, activates regulatory T cells and prevents atherosclerosis by modulating lipoprotein metabolism." (PMID 35910196, 2022). "We recently identified Foxp3 and RORγT co-expressing P6+ cells in humans and mice with atherosclerosis, although the specific role of this cell type in atherogenesis has not been clarified yet." (PMID 36684560, 2022). "The centrality of the article “Depletion of FOXP3+ regulatory T cells promotes hypercholesterolemia and atherosclerosis” is 0.11, indicating that the article is influential." (PMID 36311729, 2022). "The reduction in atherosclerosis correlated with immunoregulatory changes including increases in interleukin-10, expansion of Foxp3+ regulatory T cells, and inhibition of NF-kBp65 activation." (PMID 36290415, 2022). "Our and others' reports demonstrated that CD4+Foxp3+ regulatory T cells play significant roles in suppressing immune responses, inflammations, atherosclerosis, and antitumor immune reactions and promoting tissue regeneration." (PMID 35211628, 2022). "Together, our results provide convincing evidence that IL-35 promotes CD4+Foxp3+ Treg expansion and impedes atherosclerosis via CCR5-amplified suppressive mechanisms." (PMID 34622804, 2021). "Previous reports have demonstrated that monocyte and T cell recruitment and macrophage accumulation are found in mouse aortic and human atherosclerotic plaques; selective depletion of Foxp3+ Tregs promotes atherosclerosis in mice." (PMID 34622804, 2021). "Immature tolerogenic DCs, characterized by low expression levels of MHC class II molecule and costimulatory molecules, expand CD4+Foxp3+ Tregs and inhibit Teff responses, contributing to the maintenance of immune tolerance and regulation of atherosclerosis." (PMID 34945203, 2021). "Adoptive transfer of ApoB100-pulsed tolerogenic DCs prevented atherosclerosis development in hypercholesterolemic mice by diminishing pathogenic T cell responses to ApoB100 and promoting antigen-specific CD4+Foxp3+ Treg responses." (PMID 34945203, 2021). "Another level of complexity to the role of Tregs in atherosclerosis is that, in contrast to mice, FoxP3 is found in humans in several isoforms, including FoxP3Δ2 lacking exon 2, the dominant form in activated Tregs." (PMID 33805071, 2021). "Here, we report that hyperlipidemia induced plasma IL-35 expand the splenic CD4+Foxp3+ Tregs and support the frequencies of infiltrated Tregs in atherosclerotic aortas, which are negatively correlated with the progression of atherosclerosis." (PMID 34622804, 2021). "Further investigation found that CD4+CD25+Foxp3+ Tregs were significantly decreased in HFD-induced atherosclerosis, and the treatment with rSj-Cys significantly stimulated the proliferation of Tregs in splenocytes." (PMID 34901005, 2021). "This study identified for the first time the role of Foxp3+ Tregs in atherosclerosis and demonstrated a novel suppressive mechanism that modulates lipid metabolism other than the well-recognized inflammation regulation." (PMID 34945203, 2021). "A recent study showed that the expression of Foxp3 in Tregs and the immunosuppressive function were lost during the process of atherosclerosis, which resulted in the transformation of some Tregs into Tfhs." (PMID 33614738, 2020).
atherosclerosis (continued). "This suggests that PCAF regulates atherosclerosis via modulation of FoxP3+ regulatory T cell differentiation." (PMID 33585580, 2020). "This conclusion suggests that PCAF regulates atherosclerosis via modulation of FoxP3+ Treg differentiation." (PMID 33585580, 2020). "Low expression level of CD4+CD25+Foxp3+ Tregs was thought to be involved in the development stages of human atherosclerosis." (PMID 29976209, 2018). "Surprisingly, the administration of rebamipide upregulated the level of Foxp3, suggesting a regulatory role in the balance between Th17 and Treg cells in atherosclerosis." (PMID 28241014, 2017). "Knockdown of FOXP3 promotes the progression of atherosclerosis in mice, suggesting a possible atheroprotective function of FOXP3+ Tregs." (PMID 28589127, 2017). "In contrast, TGF-β, which is produced by many cells, such as CD4+CD25+Foxp3+ Tregs, is a protective effector in atherosclerosis." (PMID 28903402, 2017). "Our earlier Netrin1 gene therapy study demonstrated that FOXP3 and CD25 were strongly overexpressed in aortas compared to controls, and that this overexpression was associated with significantly lower atherosclerosis." (PMID 26187646, 2015). "The FOXP3 gene controls the differentiation of lymphocytes into regulatory T lymphocytes (Treg), a subset of T helper cells that inhibit atherosclerosis by modulating lipoprotein metabolism." (PMID 25016368, 2014). "In the present study we found that the frequency of FOXP3+ cells in AV as low, and in the same range as observed in native atherosclerosis." (PMID 21494640, 2011). "In an experimental model of atherosclerosis, Mor at al. have shown that oxidized lipids inhibit FOXP3 expression and attenuate suppressive properties of Treg." (PMID 21494640, 2011). "B. vulgatus attenuated atherosclerosis through Foxp3 upregulation and TNFα downregulation." (PMID 34531862, 2021). "Foxp3 + Treg inhibits atherosclerosis by modulating lipoprotein metabolism." (PMID 34915859, 2021). "Notably, the fraction of these multi-lineage committed cells increased, in particular the co-expression of the TH1 TF T-bet, in donors with subclinical atherosclerosis, while the fraction of single FoxP3 expressors decreased." (PMID 33669769, 2021). "Decreasing the number of CD4+CD25+Foxp3+ Tregs was related to the progression of atherosclerosis." (PMID 34901005, 2021). "Importantly, regulatory T cells (Tregs) expressing the IL-2 receptor α-chain (CD25) and the transcription factor FoxP3 have been shown to protect against atherosclerosis." (PMID 33805071, 2021). "Of note, these ApoB100-autoreactive CD4+ T cells are mainly comprised FoxP3+ Tregs in healthy individuals, whereas in patients with subclinical atherosclerosis, they are comprised less of Tregs and more of T-bet+ Th1 and retinoic-acid receptor-related orphan receptor (ROR)-γt+ Th17 cells." (PMID 33805071, 2021). "However, the regulation and function of FoxP3+ Tregs in atherosclerosis remains controversial: In humans, one report has suggested higher frequencies of circulating Tregs in patients with stable atherosclerosis compared with healthy controls." (PMID 33669769, 2021).
atherosclerosis (continued). "These associative findings argue against a solely protective role of Tregs and may be partially explained by the appearance of Treg-like CD4+ T cells that express FoxP3 and pro-inflammatory cytokines in advanced atherosclerosis." (PMID 33669769, 2021). "In a second experiment, in which the number of rounds was increased to three, we found that the combination of VitD and Dexa induced the highest percentage of FOXP3+ CD4+ T cells when injected either in absence or presence of the atherosclerosis-relevant antigen LDL." (PMID 32395119, 2020). "Tregs may also completely lose their Foxp3 expression during atherosclerosis and are then converted into proatherogenic T follicular helper (Tfh) cells." (PMID 32650487, 2020). "Suppressed IL-2 signaling (crucial for Foxp3 expression and Treg maintenance) and increased IL-6Rα expression (important of Tfh differentiation) were proposed to drive the conversion of Tregs into Tfh cells during experimental murine atherosclerosis." (PMID 32650487, 2020). "In the human atherosclerotic plaque, Foxp3+ Treg cells presented all stages of atherosclerosis." (PMID 29137256, 2017). "Depletion of Foxp3+ Treg cells promotes hypercholesterolemia and atherosclerosis." (PMID 29137256, 2017). "Given our recent report showing the augmented immune responses related to Th1, Th2, and Th17 cells in CD4+Foxp3+ Treg-depleted atherosclerosis-prone mice, augmentation of these helper T cell responses may be caused by dysregulated CD4+Foxp3+ Treg responses in our Ccr4-/-Apoe-/- mice." (PMID 40608058, 2025). "Cell culture studies show that retinoic acid, the transcriptionally active form of vitamin A, promotes Treg differentiation by upregulating FoxP3 expression; however, whether dietary vitamin A affects Tregs during atherosclerosis development and resolution remains unanswered." (PMID 38319073, 2024). "Thus, we suppose that DNMT3b participated in accelerating atherosclerosis may be through regulating methylation levels of Foxp3-TSDR in Tregs and suppressing Treg function." (PMID 35422896, 2022). "Moreover, our results proposed that Foxp3-TSDR hypermethylation may contribute significantly to the pathogenesis of atherosclerosis." (PMID 35422896, 2022). "The pathogenic action of Th17 cells in atherosclerosis depends on their capacity to produce proinflammatory factors, such as IL-6, IFN-γ, and GM-CSF, and some pathogenic Th17 cells are derived from Tregs that lose FOXP3 expression and immunosuppressive properties." (PMID 31653058, 2019). "Moreover, when FOXP3 is knocked down, the progression of atherosclerosis occurs in various animal models, suggesting a possible protective function of Treg cells against atherosclerosis." (PMID 31500373, 2019). "These authors showed that the depletion of Tregs caused a 2.1-fold increase in atherosclerosis without a concomitant increase in vascular inflammation, indicating that FOXP3-expressing Tregs inhibited atherosclerosis through the modulation of lipoprotein metabolism." (PMID 24991091, 2014). "Furthermore, FOXP3+ Tregs inhibit atherosclerosis by modulating lipoprotein metabolism." (PMID 25016368, 2014). "Thus, it could be that oxidized lipids, present already in the intima in the earliest stages of atherosclerosis, locally inhibit FOXP3 expression and Treg function in vivo." (PMID 17712427, 2007).
atherosclerosis (continued). "Here we highlight the most recent advances in our understanding of the roles of FOXP3-expressing CD4+ Treg cells in the atherogenic process and discuss potential translational strategies for the treatment of atherosclerosis by Treg manipulation." (PMID 37763334, 2023). "We reported that the administration of IL-27 prevents both the initiation and the progression of atherosclerosis by inducing LAP+ and Foxp3+ Tregs." (PMID 36405994, 2022). "For examples, cDC1s can drive the recruitment of IL-10-expressing CD25+Foxp3+ Tregs in nephrotoxic AKD, liver IRI, crescent glomerulonephritis, as well as atherosclerosis." (PMID 34234783, 2021). "CD4+CD25+Foxp3+ Treg exerts immunomodulatory effects by releasing anti-inflammatory cytokines IL-10 and TGF-β to inhibit the development of atherosclerosis possibly through promoting the conversion of M1 to M2 macrophages." (PMID 34901005, 2021). "One of these genes, Forkhead Box P3 (FOXP3), controls the differentiation of lymphocytes into regulatory T lymphocytes (Treg), a subset of T helper cells that inhibit atherosclerosis by modulating lipoprotein metabolism." (PMID 32210181, 2020). "In order to be able to track Treg during atherosclerosis and since Foxp3 is the marker that defines Treg, we needed to create a mouse model that allowed us to track Treg despite Foxp3 expression, on the assumption that Treg may lose Foxp3 expression during atherogenesis." (PMID 29545616, 2018). "Depletion of FOXP3+ Treg cells in 8- to 10-week-old DEREG promotes hypercholesterolemia and atherosclerosis." (PMID 26772975, 2016). "This is in contrast to a recent study, where we showed an increase in Foxp3 expressing regulatory T cells, after HSP treatment, in a mouse atherosclerosis model." (PMID 19142233, 2009). "We examined the mechanisms by which CCR4 deficiency accelerates early atherosclerosis by focusing on changes in systemic T cell responses, including those involving CD4+Foxp3+ Tregs and CD4+Foxp3- non-Tregs, in peripheral lymphoid tissues." (PMID 40608058, 2025). "Because proliferation of FOXP3+ Tregs can be induced by DNA methyltransferase inhibitor such as AZA and EGCG, the epigenetic regulation of the FOXP3 gene via DNMT3b shows potential therapeutic targets for atherosclerosis." (PMID 35422896, 2022). "To explore whether rSj-Cys reduces the development of atherosclerosis by stimulating Treg, we detected the Treg-expressed CD3ε, CD4, and CD25 on the surface and the intracellular expression of Foxp3 in splenocytes." (PMID 34901005, 2021). "As atherosclerosis progresses, T cells express proatherogenic Treg transcription factors, including RORγ-T (Th17), Bcl-6 (TFH), or T-bet (Th1), instead of the atheroprotective Th transcription factor FoxP3." (PMID 33613306, 2021). "We present here a study of the FOXP3 gene in a Spanish OSA cohort, which includes methylation, protein, and gene expression profiles and their relationship with apnea parameters, immunological, and subclinical atherosclerosis data." (PMID 32210181, 2020). "FOXP3 and RORC were consistently diminished in leukocytes in our T1DM patients thus indicating reduced levels of Treg like before, as well as decreased Th17, whose role in atherosclerosis is controversial." (PMID 31299986, 2019). "Thus, we developed a novel Treg lineage tracker mouse model; Foxp3-IRES-YFP-Cre-Rosa26-loxp-td-RFP-loxp-ApoE−/− (LT-ApoE−/−) and studied these mice in the context of atherosclerosis." (PMID 29545616, 2018). "Consistent with thevariation in the T-cell subset ratio, in patients with atherosclerosis, theTh17-cell-related transcription factor RORC showed a markedly higher mRNA level(p < 0.05), conversely, the mRNA expression of the Treg cell-relatedtranscription factor Foxp3 was notably reduced (p < 0.05)." (PMID 39076663, 2022).
atherosclerosis (continued). "Conversely, a recent study investigating the development of subclinical atherosclerosis in adult patients with severe OSA found that plasma FOXP3 expression and FOXP3 intron 1 methylation was no different than that of control patients regardless of C-reactive protein expression." (PMID 34502428, 2021). "However, CD4+CD25+FoxP3+ Treg cells or CD8+CD122+ Treg cells showed a lack of selectivity for the 20μg dosed-group, suggesting that they are not involved in the protective effect on atherosclerosis." (PMID 29091929, 2017).